BBIP1 (BBSome interacting protein 1)
Description:
The BBSome complex is thought to function as a coat complex required for sorting of specific membrane proteins to the primary cilia. The BBSome complex is required for ciliogenesis but is dispensable for centriolar satellite function. This ciliogenic function is mediated in part by the Rab8 GDP/GTP exchange factor, which localizes to the basal body and contacts the BBSome. Rab8(GTP) enters the primary cilium and promotes extension of the ciliary membrane. Firstly the BBSome associates with the ciliary membrane and binds to RAB3IP/Rabin8, the guanosyl exchange factor (GEF) for Rab8 and then the Rab8-GTP localizes to the cilium and promotes docking and fusion of carrier vesicles to the base of the ciliary membrane. Required for primary cilia assembly and BBSome stability. Regulates cytoplasmic microtubule stability and acetylation.
Synonyms: BBIP10; NCRNA00081; bA348N5.3; BBS18
Tractability: No criterion of Open Targets' tractability assessment is met for any kind of drug.
Gene: Protein-coding gene on chromosome 10 (110,898,730 to 110,919,201, reverse strand). Ensembl gene ENSG00000214413.
Subcellular location: Cell projection, cilium; Cytoplasm
Subcellular location (Human Protein Atlas): Basal body; Cytosol; Nucleoplasm; Centrosome; Vesicles
Pathways (Reactome):
Organelle biogenesis and maintenance: BBSome-mediated cargo-targeting to cilium
Gene Ontology:
Molecular function: protein binding
Biological process: cilium assembly; receptor localization to non-motile cilium
Cellular component: BBSome; ciliary basal body; ciliary membrane; cytoplasm; cytosol; cilium
Genetic constraint (gnomAD): Loss-of-function variants: 3 observed, 4.09 expected, observed/expected ratio (o/e) 0.73, 90% interval 0.33 to 1.69. That is too few expected variants to judge how well the gene tolerates losing a copy. Missense variants: 59 observed, 64.16 expected, observed/expected ratio (o/e) 0.92, 90% interval 0.75 to 1.14. Synonymous variants: 16 observed, 19.87 expected, observed/expected ratio (o/e) 0.81, 90% interval 0.54 to 1.22.
Gene-disease validity (ClinGen):
ClinGen rates the evidence that BBIP1 causes each of these diseases.
ciliopathy (autosomal recessive): Definitive. A genetic disorder of the cellular cilia or the cilia anchoring structures, the basal bodies, or of ciliary function.
Homologues: Orthologues: macaque BBIP1 (84% identical), dog BBIP1 (67% identical), pig BBIP1 (65% identical), rat Bbip1 (65% identical), mouse Bbip1 (61% identical), guinea pig BBIP1 (57% identical), zebrafish bbip1 (54% identical), tropical clawed frog BBIP1 (53% identical), Caenorhabditis elegans K07C11.10 (23% identical).
Diseases named in the same sentence as BBIP1 in open-access papers:
BBIP1 is named in the same sentence as 15 diseases in open-access papers, as found by Europe PMC text mining. Sharing a sentence is not in itself a finding about the gene and the disease. The quoted sentences say what the papers report.
Bardet-Biedl syndrome (5 papers, 2014 to 2024). A ciliopathy with multisystem involvement. "BBIP1 was recently shown to cause a recessive type of Bardet-Biedl syndrome with retinitis pigmentosa, obesity, kidney failure, cognitive disability and brachydactyly, phenotypes that are obviously different from our patient." (PMID 24739123, 2014). "These include the BBSome complex, a stable heptameric structure consisting of eight subunits, namely, the Bardet Biedl Syndrome (BBS)-associated proteins and interacting proteins (BBS1, BBS2, BBS4, BBS5, BBS7, BBS8, BBS9 and BBIP10/BBS18/BBIP1)." (PMID 34356089, 2021). "The gene–disease-association in humans showed that targeted genes of fs-cb-miRs like KLHL20, BBIP1, and PAPD4 have acted as biomarkers for the diseases such as Alzheimer’s disease, Bardet-Biedl syndrome 18, and Hepatitis C virus infection, respectively." (PMID 38674383, 2024).
ciliopathies (1 paper, 2023). "Moreover, they revealed that depletion of the BBIP1 protein also significantly reduces the incorporation of the BBS4 protein into the BBSome complex, leading to an aberrant BBSome complex and ciliopathies." (PMID 37239474, 2023).
BBIP1 also shares sentences with these, for which no sentence is quoted: Alzheimer disease (1 paper); cancer (1); frontometaphyseal dysplasia (1); hepatitis C virus infection (1); kidney failure (1); Meckel syndrome type 13 (1); Meckel syndrome, type 2 (1); Obesity (1); orofaciodigital syndrome I (1); osteofibrous dysplasia (1); polydactyly (1); retinitis pigmentosa (1); spondylometaphyseal dysplasia (1).